ABCG2 (ATP binding cassette subfamily G member 2 (JR blood group))
Diseases named in the same sentence as ABCG2 in open-access papers (continued):
Sharing a sentence is not in itself a finding about the gene and the disease.
melanoma (continued). "First, high level and activity of AhR mediates the invasive/dedifferentiated phenotype of melanoma through the direct regulation of the expression of many genes involved in invasion (COL1A1, COL6A1, COL6A2, CYR61, STC2...) and dedifferentiation phenotypes (CCL2, NTM, NUAK2, SOX9, ABCG2...)." (PMID 36305167, 2022). "Interestingly, ABCB1, ABCG2, ABCB5 and ABCC1 have been found important in melanoma chemoresistance." (PMID 24098529, 2013). "IgR39 melanoma cells that are negative for CXCR6, ABCG2 or CD271 markers are sorted by flow cytometry, and then plated and grown under standard conditions." (PMID 26494317, 2015). "We sort human melanoma cells using three distinct cancer stem cell (CSC) markers — CXCR6, CD271 and ABCG2 — and observe that the fraction of non-CSC-marked cells first overshoots to a higher level and then returns to the level of unsorted cells." (PMID 26494317, 2015). "Chromatin immunoprecipitation (ChIP) using anti-SOX2 antibody followed by qPCR revealed SOX2 occupancy in the proximal promoter region of ABCG2, with a 2- to 4-fold enrichment in SOX2 signal over ChIP with nonspecific IgG in two different melanoma cell types (p < 0.05)." (PMID 35944584, 2022). "Flow cytometry showed that melanoma spheroid cells whether derived from SLM8 or from Mela1 were negative for CD133, CD20 and ABCG2." (PMID 21526207, 2011). "Therefore, we further investigated whether ABCG2 downregulation, modulated by the absence of RIPK4, enhances the sensitivity of melanoma cells to doxorubicin." (PMID 39766280, 2024).
non-small cell lung carcinoma (57 papers, 2011 to 2025). A group of at least three distinct histological types of lung cancer, including non-small cell squamous cell carcinoma, adenocarcinoma, and large cell carcinoma. "ABCG2 is a potential biomarker causing multidrug resistance (MDR) in Non-Small Cell Lung Cancer (NSCLC)." (PMID 24980828, 2014). "The primary objective of this study was to investigate the impact of ABCG2 gene expression on the non-small cell lung cancer (NSCLC) development, course of cancer disease, and patient prognosis using publicly available data." (PMID 39457707, 2024). "An in-depth study of ABCG2 gene expression becomes possible with the selection and processing of transcriptomic and epigenomic data collected during multiomics studies in non-small cell lung cancer." (PMID 39457707, 2024). "For example, miR-665 can increase the sensitivity of non-small cell lung cancer cells to chemotherapeutic drugs by downregulating the expression of ABCG2." (PMID 37894282, 2023). "In this study, a new TPT selected human non-small cell lung cancer (NSCLC)-resistant cell model NCI-H460/TPT10 with ABCG2 overexpression and its parental NCI-H460 cells were utilized to investigate the role of CBZ in drug resistance." (PMID 33829017, 2021). "To further establish the mechanistic link between ABCG2 overexpression and resistance to MLN4924, we utilized NCI-H460 non-small cell lung cancer (NSCLC) cells and their mitoxantrone-resistant variants (NCI-H460/MX20)." (PMID 32059437, 2020). "We aimed to analyze the correlation between ABCG2 genepolymorphisms of 34 GG/(GA + AA) loci, 421 CC/(AC + AA) loci, and non-small celllung cancer (NSCLC) therapeutic effects via meta-analysis." (PMID 32159608, 2020). "It has been reported that ABCG2 expression is increased in non-small cell lung cancer lines showing resistance to gefitinib, suggesting that overexpression of this transporter is one of the mechanisms underlying resistance to EGFR TKIs." (PMID 31340525, 2019). "High levels of ABCG2 have been associated with MDR in acute lymphoblastic leukemia, chronic myeloid leukemia and non-small cell lung cancer." (PMID 27689338, 2016). "They observed significantly decreased ABCG2 expression in metastatic small cell lung cancer cells compared to non-small cell lung cancer." (PMID 25268163, 2014). "The presence of ABCG2 in esophageal squamous cell carcinoma and advanced non-small cell lung cancer is significantly correlated with a decreased survival." (PMID 24626598, 2014). "The upregulation of such stem cell markers as ABCG2 and Sca-1 in the SP population isolated from D121 non-small cell lung cancer cells is also highly significant; especially as these makers are associated with multiple drug resistance." (PMID 21468047, 2011). "In addition, overexpression of ABCG2 in esophageal squamous cell carcinoma and advanced non-small cell lung cancer is correlated with significantly decreased overall survival." (PMID 32059437, 2020). "Also, EGFR inhibitor PD153035 can synergistically increase the anti-tumor effect of chemotherapy modalities via down-regulating ABCG2 in non-small cell lung cancer." (PMID 32660222, 2020). "Importantly, LBL21 exhibited the ability to abrogate stem cell-like cancer side population (SP) cells in non-small cell lung cancer A549 cells associated with a downregulation of stem cell markers including OCT4, ABCG2, SOX2 and CD133." (PMID 28640251, 2017). "In addition, a strong correlation between ABCG2/BCRP expression and the rate of response to chemotherapy or survival was found in tumor samples from 72 non-small cell lung cancer patients." (PMID 22355323, 2012). "Moreover, miR-495 could reverse cisplatin resistance in non-small cell lung cancer by regulating the expression of the drug resistance genes ABCG2 and ERCC1 and directly targeting UBE2C 3′-UTR, affecting cells growth, invasion, and metastasis." (PMID 34935899, 2022).
non-small cell lung carcinoma (continued). "LCA has been shown to significantly alter the chemosensitivity of R482-HEK293 (ABCG2-transfected HEK293 human cells), S1-M1-80 (human colon cancer) and H460-MX20 (human non-small-cell lung cancer NSCLC) cells." (PMID 36232899, 2022). "In most cell lines, the ABCB1 promoter was higher methylated than the ABCG2 promoter, with the exception of the two small cell lung cancer cell lines GLC-4 and DMS114, the non-small cell lung cancer cell line A549 and the prostate cancer cell line PC-3." (PMID 27689338, 2016). "It has been reported that chemotherapeutic efficacy in patients of non-small cell lung cancer is positively correlated with the level of ABCG2 expression and independent on ABCB1, ABCC1 and ABCC3, suggesting that specific suppression of ABCG2 may help to circumvent MDR in these patients." (PMID 28059154, 2017). "For human Non-Small Cell Lung Cancer (NSCLC) cell lines, excluding 0.03 - 6.1% of the tumor cells which were SP cells, the presence of a Hoechst dye 33342 showed elevated expression of ABCG2, an increased tumorigenicity in mice resistant to various chemotherapeutic agents." (PMID 26515463, 2015). "As for human Non-Small Cell Lung Cancer (NSCLC) cell lines, the presence of a Hoechst dye 33342 extruding in SP cells, which accounted for 0.03 - 6.1% of the tumor cells, have shown elevated expression of ABCG2, increased tumorigenicity in mice, and resistance to various chemotherapeutic agents." (PMID 24980828, 2014).
hepatocellular carcinoma (56 papers, 2011 to 2025). A malignant tumor that arises from hepatocytes. "ABCG1 upregulation was linked to oxaliplatin resistance in hepatocellular carcinoma while ABCG2 is known for promoting the efflux of a variety of substrates including cytotoxic agents." (PMID 37297005, 2023). "The ABCG2, which highly expressed in hepatoma SP cells, is associated with drug efflux related to the resistance of doxorubicin and considered as a cause of poor response of hepatoma patients to this drug." (PMID 23097677, 2012). "However, based on previous studies, several researchers found some evidence that certain genes may predispose patients to liver or ICP disease, such as ABCB9 associated with hepatocellular carcinoma and ABCG2 associated with ICP." (PMID 33546617, 2021). "We therefore conclude that ABCG2’s role in hepatocellular carcinoma prevention by quercetin via urate modulation warrants more research." (PMID 40282409, 2025). "ABCB1 and ABCG2 were mainly expressed in well-differentiated hepatoma cells, whereas poorly differentiated hepatoma cells expressed ABCC1 and ABCB2 (TAP1), accompanied by aberrant activation of the Hh signaling." (PMID 33440657, 2021). "Since data on ABCG2 expression in liver malignances are scanty, here we report the expression of ABCG2 in adult human hepatocellular carcinoma (HCC) in both in vivo and in vitro models with different degree of malignancy." (PMID 23153066, 2012). "In cell lines derived from human hepatocellular carcinoma, ABCG2 gene expression was assessed by reverse transcription quantitative real time PCR and function by Hoechst 33342 efflux assay; protein content was assessed by SDS-PAGE Western blot." (PMID 23153066, 2012). "Furthermore, it mediates chemoresistance through the ABC transporter G2 (ABCG2) in breast cancer, while, in hepatocellular carcinoma (HCC), it contributes to resistance via activation of the MAPK signaling pathways." (PMID 40265417, 2025). "Moreover, other genomic variants (g.89073197A>G and g.88924371A>G) increase the ability of ABCG2 gene to bind to nuclear proteins in human hepatoma HepG2 cells." (PMID 35582588, 2019). "BCRP (ABCG2) 34 G > A and ABCG2 1143 C > T polymorphisms were significantly associated with the lowest sorafenib plasma levels of the patients during the treatment with sorafenib of hepatocellular carcinoma." (PMID 30909474, 2019). "Further the molecular basis of anti-proliferative effect of SF-GNP nanoconjugate was identified by relative quantification of extracellular matrix factor (CD147), tumor growth factor (TGF-β), hepatoma upregulated protein (hURP) and drug transporter (ABCG-2) transcripts." (PMID 28819176, 2017). "Two ATP-binding cassette transporters, ABCB1/MDR1 and ABCG2/BCRP, are considered the most critical determinants for chemoresistance in hepatocellular carcinoma." (PMID 34031441, 2021). "For example, Tu sensitized hepatocellular carcinoma to cisplatin-induced apoptosis and reversed drug resistance by regulating the DPAGT1/Akt/ABCG2 pathway." (PMID 30413206, 2018). "ABCG2-positive cells from hepatocellular carcinoma (HCC), displayed enhancements in tumorigenicity, proliferation capacity, doxorubicin resistance, cell migration, and invasion potential, whereas ABCG2 down-expression by siRNA significantly blocked these malignant properties." (PMID 25474134, 2014). "In hepatocellular carcinoma, MDR is mediated by ABCB1, ABCB5, ABCC1, ABCC2, and ABCG2." (PMID 36557005, 2022). "In patients with hepatocellular carcinoma (HCC) recurrence, the majority of hepatic stem/progenitor cell (HSC/HPC) biomarkers are overexpressed, including cytokeratin 19, ABCG2, CD133, Nestin, and CD44, and angiogenesis agents CD34, VEGF, and PD-ECGF." (PMID 32466488, 2020). "After sorting and subsequent culture, the SP cells from Huh7 hepatoma cells appear to have higher clonogenicity and mRNA expressions of stemness genes such as SMO, ABCG2, CD133, β-catenin, and Oct-4 than those of non-SP cells." (PMID 23097677, 2012).
gastric cancer (53 papers, 2011 to 2026). A primary or metastatic malignant neoplasm involving the stomach. "In fact, GLI1 protein was shown to be associated with the promoter fragment of ABCG2 through a Gli-binding consensus site in gastric cancer cells." (PMID 28404967, 2017). "More importantly, we have shown that higher GLI1/ ABCG2 expression is associated with poor survival of gastric cancer patients who underwent CDDP-based chemotherapy." (PMID 28404967, 2017). "The relevance of our studies to gastric cancer patient care is reflected by our discovery that high ABCG2 expression was associated with poor survival in the gastric cancer patients who underwent chemotherapy." (PMID 28404967, 2017). "Our findings indicate that ERK signaling functionally contributes to ABCG2-associated multidrug resistance and aggressive phenotypes in PTX-resistant gastric cancer cells." (PMID 42278563, 2026). "We chose a set of genes that were reported to encode gastric cancer stem cell markers such as LGR5, CD133, CD44, CD54, ABCG2 and MSI1, and then performed qPCR to detect their expression in both NANOGP8-transfected (SGC7901-NANOGP8) and mock cells (SGC7901-NC)." (PMID 29689047, 2018). "The expression level of ABCG2 was analyzed by immunohistochemistry in 180 cases of gastric cancer patients who underwent chemotherapy." (PMID 28404967, 2017). "According to our criteria, 62% (111/180) of gastric cancer specimens were positively stained with anti-ABCG2 antibodies." (PMID 28404967, 2017). "Targeting ABCG2 will be a more feasible strategy to improve the sensitivity of gastric cancer cells to chemotherapy." (PMID 28404967, 2017). "From all these data, we conclude that activation of Hh signaling, through regulation of ABCG2, plays an important role in regulation of drug sensitivity in gastric cancer." (PMID 28404967, 2017). "We went further to find the relevance of our data to gastric cancer patients by correlating ABCG2 expression in the tumor with the survival of patients who underwent chemotherapy using CDDP." (PMID 28404967, 2017). "Our results indicate that the GLI1-mediated regulation of ABCG2 is an important mechanism responsible for maintenance of the residual cancer cells (or putative cancer stem cells) in gastric cancer following treatment with CDDP, a major chemotherapeutical drug." (PMID 28404967, 2017). "The presence of ABCG2 was higher in poorly differentiated gastric cancer specimens in comparison with well-differentiated ones (P = 0.0005)." (PMID 28404967, 2017). "The present study found that the NSAID celecoxib reduces HIF-2α, Oct-4 and ABCG2 mRNA and protein expression in gastric cancer tissues implanted in nude mice." (PMID 25452783, 2015). "Developing such liposomal irinotecan formulations with EGFR or ABCG2 inhibitors could be a safer approach to achieving synergy with irinotecan in gastric cancer and other gastrointestinal cancers." (PMID 39033209, 2024). "However, evaluation of the expression levels of PEPT1 and ABCG2 seems to be useful in predicting the effectiveness of 5-ALA PDD in stomach cancer, since PEPT1 and ABCG2 seem to be key players in controlling intracellular PpIX levels in stomach cancer cells." (PMID 35742921, 2022). "In the Venn diagram intersection of recognized targets about identified chemical compounds and gastric cancer, a total of 23 gastric cancer genes are acquired among which the top six genes ABCG2, MUTHY, TRET, POLE, BRAF and G, and FGFR2 were used to produce Venn diagram." (PMID 36500601, 2022). "In addition, CD44, Wnt2, Bmi1, Notch1, Oct4, Sox2, Nanog, C-mys, ABCG2, CXCR4 and other “stemness associated genes” are highly expressed in the CD44+ gastric cancer cell population." (PMID 36316684, 2022). "Moreover, miR-132 has been reported to regulate the SIRT1/CREB/ABCG2 signaling pathway, contributing to cisplatin resistance and serving as a novel therapeutic target against gastric cancer." (PMID 35336739, 2022).
gastric cancer (continued). "Moreover, knockdown of HOTAIR inhibited expression of the multidrug-resistance genes ABCB1, ABCC1, and ABCG2 in cisplatin-resistant gastric cancer cells and reduced xenograft tumor growth in nude mice." (PMID 36471329, 2022). "The effect of ectopic ABCG2 expression on the IC50 of CDDP was very similar to that GLI1 expression, suggesting that ABCG2 may be the major mediator for regulating drug sensitivity in gastric cancer." (PMID 28404967, 2017). "Furthermore, we established scoring guidelines for ABCG2 expression based on the clinically used guidelines for HER2 immunohistochemistry assessment in gastric cancer." (PMID 27257141, 2016). "NANOGP8 may confer gastric cancer cells with chemoresistance by upregulation of ABCG2." (PMID 36176765, 2022). "Moreover, inhibition of ABCG2 expression by genistein, which is the predominant isoflavone in soy products, could inhibit gastric cancer stem cell-like features and reduce the chemoresistance of GCSCs." (PMID 36176765, 2022). "Hh signaling has also been shown to regulate ABCG2 expression to confer 5-FU and cisplatin resistance in gastric cancer (GC)." (PMID 34638233, 2021). "Although ABCG2 is a well-known drug efflux transporter, its functional contribution to paclitaxel (PTX) resistance and its relationship with ERK signaling in gastric cancer remain incompletely understood." (PMID 42278563, 2026). "Next, we screened a panel of gastric cancer cell line-derived xenograft (CDX) and disease-relevant patient-derived xenograft (PDX) lines for ABCG2 expression, using the HT29SN-38 cells as a reference." (PMID 40332396, 2025). "This study expands on BATF2's role in gastric cancer, demonstrating how it interacts with PTEN to suppress the AKT/β-catenin/ABCG2 signaling pathway, impacting stem cell markers like ABCG2, CD44, SOX2, and NANOG, based on in vivo and in vitro analyses." (PMID 39629124, 2024). "This pattern indicates that gastric cancer cells with high BATF2 levels exhibit increased vulnerability to chemotherapy, while those surviving tend to resist drugs, as indicated by heightened ABCG2 levels." (PMID 39629124, 2024). "Our data suggests that by downregulating ABCG2, BATF2 can potentially amplify the chemotherapeutic responsiveness of gastric cancer cells, offering a promising avenue for enhancing treatment efficacy." (PMID 39629124, 2024). "FGFR2, Muthy, ABCG2 and TRET are four of the top 19 target genes with the highest connections in the PPI network that are important in the fight against gastric cancer." (PMID 36500601, 2022). "-The expression of the CSC markers ABCB1, ABCG2, and CD133 differ in gastric cancers with various degrees of differentiation. -Poorly differentiated gastric cancers expressing relatively more CSC markers." (PMID 31024835, 2019). "We analyzed correlation between RPN2 and P-gp, ABCG2, or MRP1 expression in gastric cancer biopsy tissue in manner of immunohistochemical method." (PMID 29632637, 2018). "Of note, the expression of ABCG2, P-gp and MDR-1 was found to be increased in gastric cancer cell lines." (PMID 29137307, 2017). "We predict that the novel strategies aimed at reducing GLI1 expression or interrupting ABCG2 function, together with CDDP-based chemotherapy, should improve the survival of gastric cancer patients." (PMID 28404967, 2017). "Since inhibitors for GLI1 and ABCG2 are already available, we predict that these agents, together with CDDP-based chemotherapy, will improve gastric cancer patient survival." (PMID 28404967, 2017). "Blockage of ABCG2 function, via ectopic expression of a dominant negative construct ABCG2/TM5-6, made N87 gastric cancer cells more sensitive to CDDP treatment." (PMID 28404967, 2017). "In bladder cancer and gastric cancer cell lines, ALA fluorescence status closely correlates with up-regulation of PEPT1 and down-regulation of ABCG2 gene." (PMID 28257041, 2017).